EGR1 (early growth response 1)
Diseases named in the same sentence as EGR1 in open-access papers (continued):
Sharing a sentence is not in itself a finding about the gene and the disease.
melanoma (continued). "As miR146a was previously shown to regulate EGR1, we analyzed the miR146a expression in NHEM and five melanoma cell lines from the primary tumor (Mel Juso, Mel Wei, WM3211) and metastasis (Mel Im, SkMel28) by qRT-PCR and confirmed its downregulation in melanoma compared to melanocytes." (PMID 34439267, 2021). "Unlike LLC1 cells, B16F10 melanomas exhibit no alteration in Mig or in tumor growth in Egr-1-/- mice, a finding that highlights the importance of the choice of model system when examining tumor/stromal interactions." (PMID 19200397, 2009). "Along the trajectory, the gene signature of cluster 3 in melanoma cells was characterized as the activation of certain functional pathways, including the cell adhesion pathway (VIM), immune response signaling pathway (JUN, EGR1), and melanosome organization signaling pathway (MLANA)." (PMID 38862482, 2024). "Critically, the eIF4Fi-induced increase in EGR1 and c-Fos protein levels was entirely abrogated by the specific MEK inhibitor PD184352, confirming the complete dependence of the induced c-Fos and EGR1 overexpression in BRAFV600E melanoma cells on the ERK pathway activity." (PMID 39436655, 2024). "However, an EGR1 -like pattern of gene expression was observed for JUN, indicating that the intensity of expression of the EGR1, FOS, IER2, and JUN transcription factor genes could be coregulated at least in some human melanomas." (PMID 39436655, 2024). "Nevertheless, we were able to obtain reproducible up‐regulation of genes including EGR1, TXNIP, AXL, CYR61, LIMS2 and TNFRSF12A in MDA‐MB‐435s and MV3 melanoma cell lines and significant increase in protein levels as well, suggesting potential implication in other melanoma cells." (PMID 31044520, 2019).
diabetes (38 papers, 2008 to 2025). "Cognitive impairment recorded in diabetes mice were associated not only with increased levels of cytokines but also decreased Arc and Egr1 mRNA expression level in brain regions associated with learning process and memory formation." (PMID 33918576, 2021). "Egr1 encodes for early growth response-1, a zinc-finger transcription factor that can be activated by oxidative stress to promote atherosclerosis, diabetes, and pulmonary hypertension." (PMID 25517031, 2014). "Egr1 overexpression in mesangial cells induced TGF-β expression, whereas Egr1 knockdown suppressed TGF-β expression mediated by the diabetes-associated long non-coding RNA NONHSAG053901." (PMID 37373116, 2023). "Early growth response protein-1 (EGR1) is a transcription factor that plays a key role in diabetes and diabetic nephropathy." (PMID 35693742, 2022). "Early growth response 1 (Egr1) is another target gene of miR-150, and knockdown of this target alleviates the diabetes-induced inflammation in mouse mesangial cells by downregulating pro-inflammatory factors (IL-1β, IL-6, and TNF-α)." (PMID 36292956, 2022). "The significant changes in Arc and Egr1 gene expression in early stage diabetes create opportunities it possible to use them to track the progression of CNS dysfunction and also to differential disease diagnosis running with cognitive impairment." (PMID 33918576, 2021). "The analysis of gene expression showed that the presented model of diabetes had a statistically significant impact on the decrease of Arc and Egr1 mRNA expression levels in both prefrontal cerebral cortex and hippocampus (p < 0.001; p < 0.01; p < 0.05)." (PMID 33918576, 2021). "Egr1/EGR1 expression is increased in adipose tissue of obese Lep/Lep mice and patients, and of diabetic db/db mice and type 2 diabetes mellitus (T2DM) patients." (PMID 32121305, 2020). "Current research and previous studies have proved that EGR1 gene has significantly affected many aspects of diabetes and obesity." (PMID 30755828, 2019). "Diabetes mellitus mice showed a significantly reduced expression of Egr-1 endothelial downstream genes Intercellular Adhesion Molecule-1 (ICAM-1) and urokinase Plasminogen Activator (uPA), relevant for extravasation of leukocytes which promote arteriogenesis." (PMID 31284541, 2019). "Numerous studies have shown that the expression of Egr1 is dramatically triggered by hyperglycaemia in diabetes mellitus." (PMID 30887692, 2019). "Hyperglycemia-induced hyper-acetylation of Egr-1 in endothelial cells was reported to be an important event linking diabetes to accelerated atherosclerosis." (PMID 31284541, 2019). "Meanwhile, they confirmed that Egr1 was upregulated in kidney tissue from 40-week-old diabetes rats." (PMID 29681936, 2018). "Egr1 can be activated by oxidative stress to promote atherosclerosis, diabetes, and pulmonary hypertension." (PMID 25739086, 2015). "Glucose-induced expression of EGR-1 represents an early step in the development of diabetes-related cardiovascular complications." (PMID 23468876, 2013). "Venn diagram analysis revealed that seven DEGs (CXCL8, MLXIPL, CREB3L1, EGR1, NOTCH3, ACTA2, and SERPINE1) were associated with both obesity and diabetes-associated pathways, including non-alcoholic fatty liver disease, insulin resistance, thermogenesis, and apelin signaling pathways." (PMID 38570815, 2024). "In patients with diabetes, there is an increased expression of renal NOX5 associated with enhanced ROS formation and the upregulation of ROS-sensitive pathways as early growth response 1 (EGR-1), protein kinase C-α (PKC-α), and thioredoxin-interacting protein (TXNIP)." (PMID 36905456, 2023). "In vascular diseases and diabetes, there is an increase in the EGR1 protein." (PMID 38275601, 2023).
diabetes (continued). "Moreover, significant changes in Arc and Egr1 memory gene expression in early stage diabetes create opportunities it possible to use them to track the progression of CNS dysfunction and also to differential disease diagnosis running with cognitive impairment." (PMID 33918576, 2021). "In addition, EGR1 promotes also diabetic nephropathy, which is one of the most common complications of diabetes." (PMID 30755828, 2019). "As hyperglycaemia in diabetics contributes to DR, we wondered whether exposing HRVECs to high glucose (25 mmol/L) would alter Egr1 expression." (PMID 30887692, 2019). "Up‐regulation of Egr1 in diabetes‐related diseases has been noted in numerous studies." (PMID 30887692, 2019). "Conversely, NOX4 decreased following Egr1 knockdown in HK-2 cells and diabetic kidney mice." (PMID 29854821, 2018). "It has been demonstrated via various significant in vivo and in vitro experimental studies that in the setting of acute or chronic hyperglycemia (diabetes mellitus), glucose can induce the increase of pro-inflammatory transcription factors such as NF-kB, AP-1, and EGR-1." (PMID 27110221, 2016). "Mechanisms of innate immunity and TLRs are implicated in inflammation and diabetes 17,18, therefore it is of interest to determine whether reduced expression of TLR and TF by valsartan is linked with Egr-1." (PMID 25109475, 2014). "The merging of the three significantly effected networks generated a complex network with regulatory hubs formed by inflammation related genes (e.g. TNF-α, NF-κB), kinases (e.g. AKT, PI-3 kinase), and transcriptional regulators (HNF4A, EGR1, Jnk) as well as diabetes related genes (Insulin, Ins1)." (PMID 22606220, 2012). "Jamaican fruit bat renal epithelial cells were enriched for diabetes-associated motifs, such as FOXO394, and were highly enriched for human kidney phenotypes and for RAAS in particular, whereas insectivore renal epithelial cells were enriched for RAAS downregulation with EGR1 TFBS." (PMID 38195585, 2024). "Downregulating EGR1 could suppressed inflammatory responses and M1 polarization of macrophages, which is the pro-inflammatory phenotype of macrophages and accumulated in PD and diabetes." (PMID 37051594, 2023). "In addition, we demonstrated that fucoidan alleviates myofibroblast activities by targeting the MEG3/miR-181a/Egr1 axis, and this MEG3 network might depend on the type of tissues or pathogenic mechanism (areca nut chewing, diabetes, and inflammation)." (PMID 35890132, 2022). "Furthermore, the number of diabetes‐induced TUNEL (+) cells was dramatically reduced in sh‐Egr1‐treated rats compared with diabetic rats that received sh‐NC, while most of those apoptotic cells were mainly localized in the inner nuclear layer (INL) and outer nuclear layer (ONL)." (PMID 30887692, 2019). "Likewise, the genomic region within UPF1 gene, covering the top-ranked CpG site is associated with CTCF, Egr1, and two more transcription factors: MYC—involved in the pathogenesis of diabetes, and PU1—initiating insulin resistance as well as regulating lipolysis." (PMID 30545422, 2018). "In addition, insulin or glucose upregulated Egr-1 in vascular endothelial cells, suggesting that Egr-1 may play a role in the development of vascular complications from diabetes." (PMID 21365018, 2011). "A whole-transcriptome study revealed differentially expressed target genes important in obesity and diabetes-related pathways such as MLXIPL, CREB3L1, EGR1, ACTA2, SERPINE1, NOTCH3, and CXCL8." (PMID 38570815, 2024).
diabetes (continued). "The (3S)-vestitol effect in reducing the expression of Scd1, Scd2, Egr1 and its impact on increasing the Apoe, Igf1, and Fgf10 expression demonstrates the positive effects that this molecule, derived from Brazilian red propolis, may have on metabolic diseases such as atherosclerosis and diabetes." (PMID 35631379, 2022). "The double actions of EGR1 and NR1D1 in diabetes and osteogenesis indicated their potential roles in the development of diabetic OP." (PMID 36050744, 2022). "Another four TFs (JUN, EGR1, NR1D1, and ATF3) (in italic) were almost involved in all the diabetes-related term and pathways." (PMID 36050744, 2022). "To explore the molecular mechanism by which MOTS-c improves cardiac function in diabetes, we performed transcript analysis of the highly expressed CCN1, ERK1, ERK2, and EGR1 genes by qRT-PCR." (PMID 36687680, 2022). "Although not identified by 2D-DIGE as differentially expressed in experimental diabetes, MYC, along with EGR1 and the AP-1 subunit c-Fos, emerged as interconnected nodes following interrogation of differentially expressed proteins using MetaCore software." (PMID 25080971, 2014). "EGR1 and EGR2 play a key role in insulin signaling and lipid metabolism and have been involved in adipocyte differentiation programs, and RREB1 has been shown as novel candidate gene for diabetes affecting insulin sensitivity, beta-cell function and adipogenesis." (PMID 40646607, 2025).
atherosclerosis (37 papers, 2011 to 2025). A disease characterized by the build-up of fatty material and calcium deposition in the arterial wall resulting in partial or complete occlusion of the arterial lumen. "Egr-1 expression is associated with many factors linked to cardiovascular pathologies such as atherosclerosis, cardiac hypertrophy, intimal thickening after acute arterial injury, and angiogenesis." (PMID 37057102, 2023). "Vascular problems such as atherosclerosis, inflammation, coagulation, ischemia, and reperfusion damage have been linked to higher levels of EGR1 and the genes it targets." (PMID 38275601, 2023). "It has been noted that Egr-1 deficiency, either global or restricted to myeloid cells, protects the mice from atherosclerosis." (PMID 32974343, 2020). "Acetate supplementation prevented the development of hypertension in mineralocorticoid excess-treated mice and downregulated cardiac Egr1, which has been implicated in human atherosclerosis." (PMID 31995569, 2020). "Prior studies show increased expression of EGR1 is associated with atherosclerosis while EGR1 knockout mice exhibited resistance to obesity, insulin resistance and fatty liver." (PMID 30369883, 2018). "By acting as a master transcription factor, Egr-1, a zinc finger nuclear protein, regulates a set of genes implicated in the pathogenesis of atherosclerosis, with subsequent thrombosis and restenosis 11,12." (PMID 25109475, 2014). "By acting as a master transcription factor, Egr-1, a zinc finger nuclear protein, regulates a set of genes implicated in the pathogenesis of atherosclerosis, with subsequent thrombosis and restenosis." (PMID 25109475, 2014). "Unsupervised DEGs analysis of SMCs revealed increased expression in Abcb8ECKO of TGF-β-pathway genes such as Tgfb1, Tgfb2, Tgfb3, Mmp2 and Col1a1, inflammatory genes such as Ccl2 (encoding for MCP1) and Csf1 as well as atherosclerosis-associated genes including Egr1, Sqstm1, Irf1, Sox4 and Xylt1." (PMID 41252867, 2025). "The deficiency of Egr1 in ECs decreased vascular inflammation in a model of atherosclerosis." (PMID 39513364, 2024). "In addition, the protein encoded by the Egr1 gene, whose expression is induced by LPS, performs a crucial function in the progress of atherosclerosis." (PMID 35631379, 2022). "Indeed, by acting as a master transcription factor, Egr-1, a zinc finger nuclear protein, regulates a set of genes implicated in the pathogenesis of atherosclerosis, with subsequent thrombosis and restenosis 11,12." (PMID 25109475, 2014). "In addition, Egr-1 has been associated with atherosclerosis, diabetes, wound healing and tumor growth." (PMID 21595990, 2011). "For instance, Egr-1 can be activated by fluid shear stress and oxidized phospholipids, two classic risk factors for atherosclerosis, in endothelial cells; activated Egr-1, in turn, functions to up-regulate the expression of pro-atherogenic genes (e.g., tissue factor)." (PMID 32974343, 2020). "Taken together, the activation of the MAPK6‒TRIM21 ubiquitin‒proteasome complex in ECs following DSS stimulation promotes atherosclerosis by regulating endothelial inflammation through the EGR1/CXCL12 axis." (PMID 39763069, 2025). "Egr1 plays a pivotal role in the response to oxidative stress and in the pathophysiology of various diseases, including atherosclerosis and hypertension." (PMID 40806189, 2025). "Inflammatory macrophage cluster identified from an atherosclerosis mouse model showed high-level expression of various genes previously assigned to a pro-atherogenic role (e.g., Ccl3, Il1b, Il1a, Nlrp3, Cebpb, Egr1, and Phlda1)." (PMID 38149246, 2023). "Egr1 is involved in the response to mechanical or oxidative stress and, thus, the development of atherosclerosis from plaques and hypertonia." (PMID 36901771, 2023). "According to earlier findings, the Egr-1 was involved in the pathogenesis of atherosclerosis, from the development of foam cells to the onset of acute cardiovascular and cerebrovascular ischemia events." (PMID 37057102, 2023).
atherosclerosis (continued). "Egr-1 has a master regulatory role in cardiovascular diseases such as atherosclerosis and restenosis." (PMID 33922585, 2021). "Egr-1 is recognized as a key mediator of Ang II-induced intimal hyperplasia, monocyte adhesion, and atherosclerosis." (PMID 34292876, 2021). "Early growth response factor-1 (Egr-1) is an important transcription factor in promoting atherosclerosis." (PMID 33922585, 2021). "In the previous studies, EGR1 was found to involve in multiple cardiovascular pathobiology including cardiac hypertrophy, atherosclerosis, ischaemic pathology and angiogenesis." (PMID 32638546, 2020). "al. demonstrated a novel mechanism linking glucose metabolism to increased inflammatory and prothrombotic signaling in diabetic atherosclerosis via activation and post-translational modification of Egr-1." (PMID 31284541, 2019). "Several studies have shown a link between the activation of Egr-1 through hypoxia, ischemia/reperfusion, mechanical stress, shear stress, emphysema, atherosclerosis, and acute vascular injury." (PMID 31284541, 2019). "EGR1 also induces the transcriptional activation of T-bet, the master gene regulator of Th1, a T-cell subsets involved in atherosclerosis progression and plaque destabilization." (PMID 28407684, 2017). "Oxidative stress, an important player in atherosclerosis can induce Egr-1 and conversely, deletion of Egr-1 showed a protective effect in the Apo E−/− atherosclerosis mouse model." (PMID 22135674, 2011). "Furthermore, EGR1 regulates various cardiovascular diseases, including pulmonary hypertension, atherosclerosis, and cardiac hypertrophy." (PMID 37498303, 2023). "Additionally, transcription factor Egr-1, upregulated during atherosclerosis, is known to downregulate TRAIL expression in endothelial cells." (PMID 33803523, 2021). "Inhibiting the expression of Egr-1 is viewed as a potential treatment strategy for atherosclerosis." (PMID 34292876, 2021). "In summary, we propose for the first time a new working model showing that transcription factors, such as STAT3, NFκB and EGR1, increase transcript levels of various miRNAs that are unique to the four HRDs (atherosclerosis, NAFLD, obesity, and T2DM/IR) as well as shared among the HRDs." (PMID 30369883, 2018). "Egr-1 is expressed at high levels in human atherosclerosis, carotid plaques and neointimal lesions." (PMID 30391937, 2018). "The role of Egr-1 for the pathogenesis of atherosclerosis is quite well described." (PMID 23202940, 2012). "EGR1, identified as a transcription factor activated by vascular injury, has been implicated in the pathogenesis of various vascular diseases, including AAA, TAA, atherosclerosis, myocardial ischemia/reperfusion injury, hypertension, and pathological angiogenesis." (PMID 38511055, 2024). "Although the validity of this conclusion awaits further authentication in animal models, this newly identified role for SPON2 certainly renews the argument that SPON2 neutralization by targeting Egr-1/BRG1 may be a reasonable approach when devising interventional strategies against atherosclerosis." (PMID 32974343, 2020). "Though CTA-384D8.35, CTB-114C7.4 and miR-4497 have not been studied yet, their functions could be interpreted by their target genes in the ceRNA network, including inflammatory responses (CCL3, ZFP36, IER3), apoptosis (EGR1), atherosclerosis and myocardial ischemia (FOS)." (PMID 31443660, 2019). "Our RNA‐seq results and further experiments revealed that early growth response 1 (EGR1)/CXCL12 axis is the downstream effector of endothelial MAPK6 in DSS‐induced inflammation and atherosclerosis." (PMID 39763069, 2025). "Early growth response 1 (EGR1) is a transcription factor known to enhance the expression of IL1B and chemokines as well as to promote the development of atherosclerosis in mice." (PMID 35246263, 2022).